EGFR (epidermal growth factor receptor)
Diseases named in the same sentence as EGFR in open-access papers (continued):
Sharing a sentence is not in itself a finding about the gene and the disease.
lung cancer (continued). "In 2022, MD simulations together with machine learning algorithms were exploited to build a personalized drug response prediction model to prognosticate the response of lung cancer patients to the EGFR TK inhibitors gefitinib and erlotinib." (PMID 38255778, 2024). "We first reported saporin-conjugated anti-epidermal growth factor receptor (EGFR) antibody target EGFR (cetuximab) (IT-Cmab), NPe6, and light (664 nm) irradiation (i.e., iTAP) in lung cancer cells in 2022." (PMID 38790935, 2024). "Taken together, our results show for the first time that activation of the pSTAT3-EGFR axis is a novel molecular mechanism by which lung cancer cells acquire resistance to EGFR-TKIs." (PMID 39967270, 2024). "Genetic ancestry is associated with specific somatic driver mutations in EGFR, KRAS, and STK11 in lung cancer in individuals of Indigenous American ancestry relative to those of EUR or EAS ancestry." (PMID 38836758, 2024). "Our work anticipated into novel and specific EGFR-TKIs and identified new compounds with therapeutic potential against lung cancer." (PMID 38625872, 2024). "A random mutagenesis screen allowed the identification of amino acid residues in EGFR that lead to resistance to the CL-387,785 inhibitor in lung cancer cells H1975." (PMID 38255778, 2024). "The images were collected from 18,232 lung cancer patients, and the EGFR gene sequences were collected from nine cohorts in China and the United States." (PMID 38352145, 2024). "It found that single MET inhibition effectively suppresses EGFR downstream signaling and proliferation in specific lung cancer cells." (PMID 39769452, 2024). "The median CYFRA21‐1:CEA ratio was 0.395 for the ALK‐positive lung cancer group, which was significantly higher compared with 0.098 for the EGFR‐positive lung cancer group." (PMID 38400801, 2024). "These cell line-derived lung cancer spheroids together with patient tissues were used to compare treatment responses of four EGFR TKIs with respective 2D cultures." (PMID 39376603, 2024). "In our paper, we will conduct a comprehensive review of current literature on EGFR TKIs to contribute to advancements in molecular genomics and the treatment of lung cancer." (PMID 39518531, 2024). "In lung cancer, activation of the EGFR-AKT-STAT3 pathway was reported to influence antitumor immune responses by regulating programmed death ligand 1 (PD-L1) expression." (PMID 39309430, 2024). "Epidermal growth factor receptor (EGFR) mutations were discovered in patients with LUAD since the first trials targeting EGFR, targeted therapy has transformed the management of lung cancer." (PMID 38573548, 2024). "This meta-analysis evaluated 11 studies comprising 2182 patients with lung cancer and explored the efficacy and safety of EGFR-TKI plus anti-VEGFR agents as first and second-line treatment." (PMID 38539522, 2024). "In lung cancer, AXL expression was found to be directly linked to EGFR signaling, involving the MAPK and c-Jun pathway activation, again suggesting the involvement of HER ligands in AXL upregulation." (PMID 39000238, 2024). "The discovery of epidermal growth factor receptor (EGFR) gene alterations in lung cancer has fueled the development of targeted therapy using tyrosine kinase inhibitors (TKIs)." (PMID 38397426, 2024). "Here, we explored the effect of BA on the sensitization of wt-EGFR lung cancer cells to EGFR-TKIs (gefitinib and osimertinib)." (PMID 38764025, 2024). "The EGFR/PI3K/Akt/mTOR pathway governs several processes in lung cancer, including genomic stability, cell survival, senescence, angiogenesis, proliferation, metastasis, and cellular metabolism." (PMID 39682234, 2024). "Dysregulated EGFR signaling has been observed in many cancers, including breast cancer, colon cancer, and lung cancer." (PMID 38711992, 2024). "In a phase II trial, 2139 patients with advanced lung cancer were assigned to receive EGFR‐TKI (gefitinib and/or erdafinitib) or EGFR‐TKI plus metformin." (PMID 38214418, 2024).
lung cancer (continued). "Elevated YAP levels have also been detected in lung cancer patients with acquired EGFR inhibitor resistance and TAZ level was a prognostic factor in NSCLC progression." (PMID 38431606, 2024). "The discovery of EGFR-activating mutations as a predictor of patient response to EGFR tyrosine kinase inhibitors (EGFR-TKIs) represented a milestone and paradigm shift in the treatment of non–small cell lung cancer (NSCLC)." (PMID 38451729, 2024). "EGFR has been identified as a critical element in lung cancer development, with its overexpression noted in various human cancers, including NSCLC." (PMID 38685671, 2024). "Epidermal growth factor receptor (EGFR) is a major oncogenic protein, and thus EGFR-targeting therapies are widely used in patients with various types of cancer, including lung cancer." (PMID 39897079, 2024). "Here, we investigated the role of DUSP22 in lung cancer development by studying its function in suppressing hyperactive EGFR signaling, a key oncogenic driver in LUAD." (PMID 38877005, 2024). "In lung cancer cells, sialylation and fucosylation of the epidermal growth factor receptor inhibit dimerization and activation, and decreased core fucosylation has been implicated in gastric cancer carcinogenesis." (PMID 38911244, 2024). "For instance, the downregulation of miR-7, which has an aberrant expression pattern in lung cancer, has been demonstrated to inhibit the mRNA expression of EGFR and Raf1." (PMID 38355480, 2024). "Previous studies have also documented its ability to improve the therapeutic impact in lung cancer patients who receive EGFR-TKI therapy." (PMID 38943199, 2024). "Currently, ctDNA research is focused on analyzing multiple mutation information, including EGFR, ALK, and KRAS, to assess the prognosis and disease recurrence of lung cancer patients." (PMID 38561776, 2024). "The aim of this study was to detect the prevalence and types of HPV and its relation with p16, EGFR and clinical findings in lung cancer." (PMID 39205175, 2024). "In patients with EGFR-mutated lung cancer, T790M mutations, MET amplifications, and other AGAs are among the acquired mechanisms of resistance to prior EGFR therapies, allowing for therapeutic options beyond chemotherapy." (PMID 39195317, 2024). "Subsequently, several cases of EGFR fusion were reported in lung cancer, colorectal cancer, glioblastoma, and other cancers, of which lung cancer was the most common." (PMID 39054543, 2024). "Targeting EGFR has been shown to promise in the treatment of many cancers, such as breast, lung cancer and glioblastoma, through PI3K-AKT and EGFR-RAS-RAF." (PMID 38434350, 2024). "As an epidermal growth factor receptor‐tyrosine kinase inhibitor (EGFR‐TKI), osimertinib has emerged as a standard EGFR‐mutation positive treatment for non‐small cell lung cancer (NSCLC)." (PMID 38226415, 2024). "Even with our in silico bioinformatics analysis using the TCGA dataset, we found that EGFR is highly expressed in lung cancer cells, and the high expression of EGFR is correlated with the poor survival of patients with lung cancer." (PMID 39453005, 2024). "Abnormal activation of the EGFR signaling pathway serves as a driving force in lung cancer development." (PMID 39967270, 2024). "Constitutively active mutant EGFR is one of the major oncogenic drivers in non–small cell lung cancer (NSCLC)." (PMID 39041204, 2024). "Here, we have developed a working model demonstrating that DUSP22 negatively regulates cell growth and migration in lung cancer cells through EGFR/c-Met and PD-L1-dependent pathways." (PMID 38877005, 2024). "Another dual screen in EGFR-dependent PC9 lung cancer cells treated with erlotinib and the CDK7/12 inhibitor THZ1 showed that the suppression of multiple genes associated with transcriptional complexes enhanced the efficacy of the combination treatment." (PMID 38255778, 2024).
lung cancer (continued). "The CYFRA21‐1 positivity rate was significantly higher in ALK‐positive lung cancer (36%) compared with EGFR‐positive lung cancer (23%) (p = 0.034)." (PMID 38400801, 2024). "We selected 134 cases of advanced or recurrent ALK‐positive and 172 cases of advanced or recurrent EGFR‐positive lung cancer from our clinical database." (PMID 38400801, 2024). "Generally speaking, PI3K-AKT, JAK-STAT, and MAPK are the pathways that participate in the regulation of PD-L1 in wild-type EGFR lung cancer." (PMID 38426097, 2024). "The database contained 149 ALK‐positive lung cancer patients and analyses were performed on 134 patients with advanced or recurrent ALK‐positive lung cancer, which excluded recurrence‐free cases and comutations with EGFR." (PMID 38400801, 2024). "This limitation underscores the variability in cellular responses across different EGFR-mutant lung cancer models and highlights the need for alternative transfection strategies or delivery systems to fully elucidate miR200c’s role in these contexts." (PMID 39766891, 2024). "Among lung cancers with EGFR-sensitive mutations, 3.5% harbor the PIK3CA mutation; however, its influence on EGFR-TKI efficacy in EGFR-mutated lung cancer is controversial." (PMID 38398169, 2024). "We first established EGFR TKI-resistant models through long-term treatments with gefitinib (GEF) or osimertinib (OSI) in human EGFR-mutant lung cancer cell line PC9 xenograft tumors." (PMID 39687207, 2024). "Of the 49 lung cancer patients included in this study, six had both HER2 amplification and EGFR mutations." (PMID 39184039, 2024). "The EGFR-TKI representative drugs gefitinib and erlotinib increased the TAM count in the tumor stroma of patients with EGFR-mutated lung cancer and significantly attenuated therapeutic cytotoxicity." (PMID 38787372, 2024). "Lung cancer is the most common malignant tumor in the world, with the epidermal growth factor receptor (EGFR) gene playing a crucial role in the development of lung cancer." (PMID 38649732, 2024). "Collectively, these results offer a promising direction for improving EGFR-TKI resistance in EGFR-mutant lung cancer." (PMID 39766891, 2024). "In this study, the impact of the apolipoprotein B mRNA-editing catalytic subunit-like (APOBEC) enzyme APOBEC3B (A3B) on epidermal growth factor receptor (EGFR)-driven lung cancer was assessed." (PMID 38049664, 2024). "We used the CYFRA21‐1:CEA ratio to avoid the effect of cutoff values and found that the ratio was higher in ALK‐positive compared with EGFR‐positive lung cancer." (PMID 38400801, 2024). "The frequencies of EGFR fusions in pan cancer and some cancers are similar in Chinese and Western populations (TCGA), including glioma (1.37% vs. 1.46%) and lung cancer (0.236% vs. 0.20%)." (PMID 39054543, 2024). "To validate the significance of pharmacological inhibition, we used additional EGFR-mutant lung cancer cell line models and observed similar phenotypes upon EGFR TKI treatment." (PMID 38548752, 2024). "This is consistent with previous reports of mutations in lung cancer fitness, and it reflects the higher incidence of mutations such as KEAP1, NFE2L2, EGFR, and MYC." (PMID 38459554, 2024). "It suggests that environmental pollutants can influence the lung microbiome and contribute to mutations in the epidermal growth factor receptor (EGFR), which is a key driver in certain lung cancers." (PMID 39409962, 2024). "EGFR and c‐MET gene mutations can occur in both lung and gastric cancers, and the abnormal expression of c‐MET is mainly reflected in non‐small cell lung cancer." (PMID 38770671, 2024). "By RNAi-mediated knockdown of NF-κB pathway components, EGFR-mutant lung cancer cells became more sensitive to erlotinib; similar outcomes were obtained with pharmacologic inhibition of NF-Κb." (PMID 39547513, 2024). "Nonetheless, further investigation is required to clarify its exact function in interacting with the ErbB/EGFR pathway during the advancement of lung cancer." (PMID 39272883, 2024).
lung cancer (continued). "PHLDA2 expression is found to be induced by oncogenic EGFR/AKT signaling in lung cancers via the correlation of PHLDA2 expression with both p-AKT and EGFR mutations." (PMID 38921000, 2024). "One twentieth of lung cancer patients diagnosed in 2016 in Germany received at least one EGFR, ALK, or BRAF inhibitor during follow‐up." (PMID 39693368, 2024). "The epidermal growth factor receptor (EGFR) gene is the most well-studied molecular target in lung cancer and is a biomarker for predicting the effectiveness of targeted therapies." (PMID 39290244, 2024). "A significant body of evidence points to the importance of upstream regulators of STAT3 in lung cancer development, for example, EGFR and Src,34 our study highlights JAK1 as a candidate kinase for STAT3 phosphorylation and activation in LUSC." (PMID 39099000, 2024). "As most of the cancer cells including lung cancer cells express high levels of EGFR, we engineered the HUVEC-EVs via postinsertion of GE11 peptide, which has been reported to interact with the EGFR receptor." (PMID 39453005, 2024). "EGFR mutations are found in approximately 50% of cases recorded in Asian populations, whereas KRAS mutations predominate in Caucasian lung cancer populations with a frequency of 30–35%." (PMID 38313018, 2024). "In our study, a great antitumor effect was observed after treatment of EGFR positive lung cancer cells with exoscFv/siLPCAT1 compared to exoscFv/siNC both in vivo and in vitro." (PMID 38589859, 2024). "miRNA-23a has been shown to inhibit the effectiveness of lung cancer drugs such as EGFR-targeted tyrosine kinase inhibitors by suppressing their ability to phosphorylate PI3K and AKT in lung CSCs, thereby preventing the induction of apoptosis in the cells." (PMID 39239557, 2024). "Brain metastases (BM) are common in patients with epidermal growth factor receptor (EGFR)‐mutant non‐small cell lung cancer (NSCLC) and confer poor prognoses." (PMID 38666433, 2024). "Functionalizing AuNPs with peptides or antibodies specific to lung cancer biomarkers, such as epidermal growth factor receptor (EGFR), enables targeted therapy that lowers off-target effects while improving therapeutic outcomes." (PMID 39458600, 2024). "Previous studies have demonstrated that nicotine stimulates epidermal growth factor (EGF) secretion and results in EGFR expression to induce the tumorigenesis of lung cancer." (PMID 37692503, 2024). "In 52 patients with EGFR-mutant lung cancer receiving erlotinib treatment, higher expression of the NF-κB inhibitor IκB was associated with a better response to therapy and a higher survival rate." (PMID 39547513, 2024). "EGFR is overexpressed in approximately 60% of individuals with non-small cell lung cancer (NSCLC), the most prevalent type of lung cancer and the primary cause of cancer-related deaths globally." (PMID 38625872, 2024). "We looked at the distribution of breakpoints in ALK, RET, ROS1, NTRK1, as well as other kinase genes known to generate oncogenic fusions in lung cancer, such as EGFR, ERBB4, MET, FGFR3, and EPHA245." (PMID 38877018, 2024). "Another cohort study examined the efficacy of EGFR-TKI in patients with lung cancer coexisting with TB." (PMID 39868375, 2024). "ADAMTS18 has also been illustrated to increase lung cancer cell sensitivity to cisplatin by suppressing the EGFR/AKT signaling pathway." (PMID 38482210, 2024). "A single-cell transcriptomic analysis of data from patients with lung cancer (GEO: GSE127465) revealed cell-type-specific distribution of EGFR in the lung cancer TME." (PMID 39453005, 2024).
lung cancer (continued). "In our study, 49 (12.5%) of the lung cancer patients treated with EGFR, ALK, or BRAF inhibitors were diagnosed at a non‐advanced stage." (PMID 39693368, 2024). "A clear cytoplasmic fluorescent signal of PKH76 (green) in EGFR positive lung cancer PC9 cells was observed, which represents the uptake of exoscFv and exoctrl." (PMID 38589859, 2024). "The level of EGFR expressed in the plasma of patients with lung cancer is significantly elevated compared to that of healthy individuals." (PMID 39464709, 2024). "Their study demonstrated that adaptive activation of AXL engages endogenous hypermutators in lung cancer cells treated with EGFR inhibitors." (PMID 38338651, 2024). "In EGFR-mutant lung cancer, hypoxia has been shown to activate the VEGF pathway and a dual blockade is being suggested as a promising therapeutic activity." (PMID 38200568, 2024). "For instance, the presence of tumor-associated proteins such as EGFR, PD-L1, and TGF-β1 in EVs has been linked to lung cancer." (PMID 39202011, 2024). "In our preliminary study, we investigated the clinical value of dPET/CT in the differential diagnosis, N-staging, and epidermal growth factor receptor (EGFR) status prediction of lung cancer." (PMID 39078558, 2024). "Up-regulation of lncRNA H19 induces ferroptosis and enhances the sensitivity of EGFR-TKI resistant lung cancer to erlotinib." (PMID 38515565, 2024). "Primary and acquired drug resistance significantly limit the clinical effectiveness of EGFR-TKIs in the treatment of lung cancer." (PMID 39196297, 2024). "After 5 months, the lung cancer progressed, prompting a switch to a combination of erlotinib (another EGFR inhibitor) and ramucirumab (a VEGFR inhibitor)." (PMID 39881923, 2024). "Treatment of prostate and lung cancer cells with the FASN inhibitor cerulenin or the palmitoylation inhibitor 2-bromopalmitate (2-BP) reduces EGFR levels on the plasma membrane while increasing lysosome levels." (PMID 38415253, 2024). "EGFR, as a member of the ErbB family, promotes malignant cell survival, proliferation, etc. through a series of biochemical processes, making EGFR and its downstream signalling pathway an important target for lung cancer therapy." (PMID 39391313, 2024). "Cell culture and animal-related studies validated that the application of pitavastatin inhibited the proliferation of lung cancer cells, promoted cell apoptosis, and restrained the acquired resistance to EGFR-TKIs." (PMID 38943199, 2024). "Recent studies have demonstrated that FZYA can effectively enhance the therapeutic effects of EGFR-TKIs in lung cancer treatment." (PMID 39735556, 2024). "From these efforts, we identified genotype-directed targeted therapies as drugs that make EGFR mutant lung cancer cells more vulnerable to macrophage attack." (PMID 38483480, 2024). "Several studies concentrated EGFR exon 19 variations of lung cancer patients among Chinese population." (PMID 38245692, 2024). "Common signal pathways involved with advanced lung cancer, were epidermal growth factor receptor/Kirsten rat sarcoma/anaplastic lymphoma kinase (EGFR/KRAS/ALK) and C-X-C motif chemokine ligand 12/C-X-C motif chemokine receptor 4 (CXCL12/CXCR4)." (PMID 38711158, 2024). "Previous studies revealed that a short duration of response to EGFR-TKIs correlated with benefit of ICI treatment in patients with EGFR-mutant lung cancers." (PMID 38347279, 2024). "This underscores the critical need for new anticancer agents that can counteract the resistance to EGFR-TKIs in lung cancer cells." (PMID 38794196, 2024). "It has been shown that RYBP inhibits the progression and metastasis of lung cancer by suppressing EGFR signaling and EMT, and high levels of PKP1 are important to maintain a high expression of vimentin, which is a key regulator of EMT and metastasis." (PMID 38785968, 2024). "EGFR is an important biomarker identified as a potential “target” for personalized treatments in lung cancer." (PMID 38279998, 2024).